KEAP1 (kelch like ECH associated protein 1)
Diseases named in the same sentence as KEAP1 in open-access papers (continued):
Sharing a sentence is not in itself a finding about the gene and the disease.
age-related macular degeneration (2 papers, 2017 to 2025). Age-related loss of vision in the central portion of the retina (macula), secondary to retinal degeneration. "In age related macular degeneration (AMD), excessive reactive oxygen species (ROS) activate mitophagy in the retinal pigment epithelium (RPE) via the p62/Keap1/Nrf2 axis." (PMID 41234227, 2025).
atopic dermatitis (2 papers, 2022 to 2025). "For instance, syringic acid alleviates C. acnes-induced inflammation by activating Nrf2 and suppressing ROS accumulation, while gentiopicroside reduces ROS levels in TNF-α/IFN-γ-stimulated keratinocytes by regulating the Keap1–Nrf2 axis in an atopic dermatitis model." (PMID 40573738, 2025).
Atrophy (2 papers, 2019 to 2021). Any weakening or degeneration, especially through lack of use. "We had previously reported that pancreas-specific mutant K-ras expression and Keap1 deletion resulted in progressive pancreatic atrophy." (PMID 33672789, 2021). "Further studies have shown that Nrf2 deletion can rescue the phenotypic changes in KC::Keap1 mice, which confirms the role of Nrf2 in pancreatic atrophy." (PMID 31511020, 2019). "Interestingly, the simultaneous activation of Kras and Nrf2 by Kras mutation and Keap1 deletion, respectively, does not promote PC development as expected but causes pancreatic atrophy." (PMID 31511020, 2019).
bipolar disorder (2 papers, 2018 to 2022). A disorder of the brain that causes unusual shifts in mood, energy, activity levels and the ability to carry out day-to-day tasks. "A study using postmortem brain samples showed decreased expressions of Keap1 and Nrf2 in the parietal cortex from patients with MDD and bipolar disorder compared to control group." (PMID 30386243, 2018).
cervical squamous cell carcinoma (2 papers, 2015 to 2022). A squamous cell carcinoma arising from the cervical epithelium. "Among Uighur women, the incidence of cervical squamous cell carcinoma (CSCC) and cervical intraepithelial neoplasia (CIN) was associated with elevated nuclear expression of NRF2 and decreased cytoplasmic expression of Keap1." (PMID 26247201, 2015).
dementia (2 papers, 2023). Loss of intellectual abilities interfering with an individual's social and occupational functions. "Observed associations of polymorphisms in CAT, GSTP1, NFE2L2 and KEAP1 with dementia support the importance of antioxidative mechanisms in AD." (PMID 36829875, 2023). "Among antioxidative genes, CAT, GSTP1, NOS1, NFE2L2, and KEAP1 were associated with dementia or AD." (PMID 36829875, 2023). "Multiple effects of NFE2L2 and KEAP1 on dementia and AD were found in our study." (PMID 36829875, 2023).
E. coli infection (2 papers, 2019 to 2025). "In this study, the expression of KEAP1 (a negative regulator of NRF2) decreased as the duration of E. coli infection increased, while the expression of NRF2 was similarly inhibited." (PMID 41413615, 2025). "Consistently, with SIM approach, Mst1 protein was condensed and formed large aggregates after E. coli infection (from 5 min and at least last for 60 min), and Keap1 co-localized with Mst1 after E. coli infection at 5/15/30 min time points, but not at 60 min in BMDM." (PMID 30765703, 2019). "Moreover, we found that Keap1 can bind to Mst2 and their interaction was enhanced upon E. coli infection or antimycin A treatment." (PMID 30765703, 2019).
fibrosis (2 papers, 2017 to 2025). the formation of excess fibrous connective tissue in an organ or tissue in a reparative or reactive process. "The activity of Keap1/Nrf2 pathway increases in response to oxidative stress and leads to upregulation of antioxidant genes to combat oxidative stress in several fibrosis models." (PMID 29113120, 2017). "Overall, our data showed that cardiomyocyte-specific activation of NRF2 via knockout of Keap1 protects the heart against pressure overload-induced cardiomyocyte cell death, cardiac fibrosis, and contractile dysfunction but without significantly affecting the extent of hypertrophy." (PMID 39657243, 2025).
fumarate hydratase deficiency (2 papers, 2017 to 2025). "Finally, there is evidence of a possible interaction of fumarate accumulating in cells accompanied with fumarate hydratase deficiency with the KEAP1 protein, which leads to activation of the NRF2 transcription factor." (PMID 40071074, 2025).
glaucoma (2 papers, 2017 to 2020). Increased pressure in the eyeball due to obstruction of the outflow of aqueous humor. "The effects of EVs derived from oxidative stressed cells on the activation of the nuclear factor erythroid 2-related factor 2-Kelch-like ECH-associated protein 1 (Nrf2-Keap1), a major OS pathway, and of the Wnt pathway, known for its role in primary open-angle glaucoma, were evaluated." (PMID 32854215, 2020).
Graves disease (2 papers, 2016 to 2025). Graves' disease is an autoimmune disorder that leads to overactivity of the thyroid gland (hyperthyroidism).It is caused by an abnormal immune system response that causes the thyroid gland to produce too much thyroid hormones. "Of the 5 probands with KEAP1 germline mutations, 1 had Graves disease with excessive hormone production, while the remaining 4 had normal thyroid function, indicating that normal hormone production is sufficient for developing thyroid hyperplasia." (PMID 39373520, 2025).
hyperthyroidism (2 papers, 2020 to 2024). Overactivity of the thyroid gland resulting in overproduction of thyroid hormone and increased metabolic rate. "Accordingly, MO Extract was used in this investigation to assess its preventive properties against induced hyperthyroidism in a rat model as well as its regulatory effects on deranged redox balance and inflammation as well as the Nrf2/Keap-1 pathway." (PMID 38303002, 2024). "Accordingly, these results might strengthen the hepatoprotective effect of MO Extract in a rat model of hyperthyroidism by regulating the Nrf-2/ Keap-1 pathway." (PMID 38303002, 2024). "Accordingly, our hypothesis was to evaluate whether MO Extract could alleviate the hyperthyroidism-induced hepatic damage by attenuation of the deranged redox balance and inflammation as well as modulation of the Nrf2/Keap-1 pathway." (PMID 38303002, 2024). "Moreover, it alleviated hyperthyroidism-induced hepatic damage by inhibiting the hepatic enzymes’ activities as well as enhancing the production of proteins concomitant with improving cellular redox homeostasis by attenuating the deranged redox balance and modulating the Nrf2/Keap-1 pathway." (PMID 38303002, 2024).
Hypoglycemia (2 papers, 2015 to 2017). A decreased concentration of glucose in the blood. "Pretreatment with protease inhibitor MG132, or selective knock-down of Siah2 (but not Keap1) significantly attenuated hypoglycemia-induced Nrf2 destabilization." (PMID 25807533, 2015). "We provided a mechanistic insight in which increased expression of Siah2 (but not Keap1) by hypoglycemia targets endothelial Nrf2 for proteasomal degradation." (PMID 25807533, 2015). "Interestingly, our data also suggested that Siah2 (but not other repressors such as Keap1) primarily contributed to hypoglycemia-induced suppression of Nrf2 protein in BBB, as knockdown of Keap1 expression did not alter hypoglycemia-induced Nrf2 suppression." (PMID 25807533, 2015).
Infertility (2 papers, 2019 to 2021). "Our results show that management of OS through activation of Nrf2/Keap1 pathway by oral DMF administration may lead to improved ovarian reserve, and this may become a solution for infertility treatment." (PMID 30760288, 2019).
influenza (2 papers, 2022 to 2023). An acute viral infection of the respiratory tract, occurring in isolated cases, in epidemics, or in pandemics; it is caused by serologically different strains of viruses (influenzaviruses) designated A, B, and C, has a 3-day incubation period, and usually lasts for 3 to 10 days. "We therefore tested whether augmenting NRF2 signaling by knocking-down expression of its inhibitor KEAP1 in A549 cells would potentiate the anti-influenza effect." (PMID 37459366, 2023). "Future studies should, therefore, explore to what extent activators of NRF2 signaling inhibit influenza or other viruses via XPO1, KEAP1, a combination of the two, or yet other targets." (PMID 37459366, 2023). "Blocking XPO1-mediated nuclear export may, thus, constitute a “noncanonical” mechanism of anti-influenza activity of electrophilic NRF2 activators that can interact with similar cysteine environments at the active sites of XPO1 and KEAP1." (PMID 37459366, 2023).
intoxication (2 papers, 2019 to 2024). Disturbances in psychophysiological functions and responses as a result of administration or ingestion of a psychoactive substance. "Taken together, BBR has a protective effect against CPS-induced renal intoxication via its antioxidant, anti-inflammatory, and anti-apoptotic effects by regulating Keap1/Nrf2/HO-1 and apoptosis signaling pathways." (PMID 38327393, 2024).
keratoconus (2 papers, 2020 to 2024). A degenerative, structural disorder of the eye, characterized by a cone-shaped protrusion of the cornea. "Thus, we localized KEAP1 and NRF2 proteins in control DN and keratoconus corneas by immunofluorescence (IF) staining in 3 different DN and KCN corneas." (PMID 32555404, 2020).
kidney (2 papers, 2017 to 2019). "The renal phenotypes were recapitulated by renal tubular-specific Keap1 deletion during development but not adulthood, indicating that renal activation of Nrf2 at an early stage is responsible for the polyuria and kidney damage observed in NEKO mice." (PMID 28233855, 2017).
lentivirus infection (2 papers, 2022 to 2024). Virus diseases caused by the Lentivirus genus. "Conversely, inhibiting endogenous Nrf2 expression through transfection of Nrf2-siRNA or transient lentivirus infection containing Keap1 impedes neuronal differentiation." (PMID 39199215, 2024). "Through lentivirus infection, two cell lines (Keap1-Restored and Keap1α-Restored) were constructed on the base of Keap1−/− cells and confirmed by real-time qPCR and Western blotting." (PMID 36142252, 2022).
Lewis lung carcinoma (2 papers, 2011 to 2024). "To address this, we stably expressed KEAP1 in mouse Lewis lung carcinoma (LLC) cells, followed by their subcutaneous injection into C57BL/6 mice." (PMID 38413563, 2024).
lipid metabolism disorders (2 papers, 2022 to 2025). "Mechanistically, this study confirmed that AMPK exerts its beneficial role in relieving of lipid metabolism disorders, oxidative stress and inflammatory response triggered by PO by activating the NRF-2/KEAP1 pathway and inhibiting the NF-κB pathway." (PMID 36160867, 2022).
male infertility (2 papers, 2023 to 2024). The inability of the male to effect fertilization of an ovum after a specified period of unprotected intercourse. "The causes of male infertility, the role of oxidative stress in male infertility and the Keap1-Nrf2 antioxidant pathway are reviewed." (PMID 38397791, 2024). "The results further emphasized the regulatory role of JAK2/STAT3 on spermatogenesis, Keap1/Nrf2 signaling, and maintenance of the testicular redox balance to combat testicular dysfunction and male infertility." (PMID 37759514, 2023).
mesothelioma (2 papers, 2021 to 2022). A usually malignant and aggressive neoplasm of the mesothelium which is often associated with exposure to asbestos. "So, in our MPM models, the expression of Nrf2, in mesothelioma, remains to be confirmed if it is associated with possible mutations of KEAP-1." (PMID 33799965, 2021).
Myocardial fibrosis (2 papers, 2022 to 2023). "Inhibition of BRD4 attenuates TGF-β-induced endothelial-mesenchymal transition and cardiac fibrosis and BRD4 may act as a Keap1/Nrf2 upstream regulatory target to regulate oxidative stress and myocardial fibrosis." (PMID 37699016, 2023). "Keap1/Nrf2 may participate in myocardial fibrosis by inhibiting oxidative stress." (PMID 37699016, 2023). "Studies have demonstrated that puerarin can prevent cardiac fibrosis by downregulating Keap1 and promoting NRF2 expression and nuclear translocation in mouse models of myocardial fibrosis." (PMID 35721561, 2022).
neuroendocrine carcinoma (2 papers, 2020 to 2021). A malignant neuroendocrine neoplasm composed of cells containing secretory granules that stain positive for NSE and chromogranin.
neuropathy (2 papers, 2017 to 2022). A disorder affecting the nervous system that manifests with pain, tingling, numbness, and/or muscle weakness. "Reduced antioxidant system and Keap1 variants are involved in the pathogenesis of T2DM and its complications of neuropathy and retinopathy." (PMID 34861061, 2022). "Looking towards the future, we must continue to validate the Nrf2/Keap1/ARE pathway as a mediator of the oxidative stress underlying TIIDM and further explore this role in less morbid complications such as retinopathy and neuropathy." (PMID 28913364, 2017). "Our results showed that neuropathy patients had a higher frequency of minor genotype of AA compared to retinopathy patients and individuals without the complication that might results in increased Nrf2 and decreased Keap1 contributing to diabetic neuropathy." (PMID 34861061, 2022). "T2DM with neuropathy had lower levels of GSH, GPx, and TAC and higher levels of TOS, MDA, and OSI and a higher frequency of Keap1 AA genotype." (PMID 34861061, 2022). "The present study detected a significantly higher frequency of minor Keap1 AA genotype in T2DM with neuropathy compared to those diabetic patients without complication and also compared to controls." (PMID 34861061, 2022). "According to the literature, there is no available report related to the frequency of Keap1 variants in T2DM and its complications of retinopathy and neuropathy and their influence on the risk of T2DM and its complications." (PMID 34861061, 2022). "A significantly higher Keap1 AA genotype was found in patients with neuropathy than T2DM without complication and controls." (PMID 34861061, 2022). "Further, the present study detected a significantly higher frequency of AA genotype in T2DM with neuropathy compared to those diabetic patients without complication and also compared to controls that might result in increased Nrf2 and decreased Keap1 expression contributing to diabetic neuropathy." (PMID 34861061, 2022).
nonalcoholic steatohepatitis (2 papers, 2017 to 2024). "Control mice (c-metfx/fx), single c-met knockouts (c-metΔhepa), and double c-met/Keap1 knockouts (met/Keap1Δhepa) were then fed a chow or a methionine-choline-deficient (MCD) diet, respectively, for 4 weeks to reproduce the features of nonalcoholic steatohepatitis." (PMID 28676836, 2017).
osteoarthritis (2 papers, 2020 to 2024). A noninflammatory degenerative joint disease occurring chiefly in older persons, characterized by degeneration of the articular cartilage, hypertrophy of bone at the margins and changes in the synovial membrane. "Multiple previous studies have mentioned that inhibiting Keap1 to activate the Nrf2 pathway alleviates OS in rats with diabetic cataracts and osteoarthritis." (PMID 38733688, 2024).
osteonecrosis (2 papers, 2021 to 2023). A none disease characterized by death of bone tissue due to a lack of blood supply. "The Venn diagrams showed six intersecting genes related to osteonecrosis of the femoral head, OS and APO targets: NFE2L2 (Nrf2), ERN1, PDGFRB, PDGFRA, KEAP1 and CDK1." (PMID 37749949, 2023).
ovarian clear cell cancer (2 papers, 2016 to 2024). An invasive malignant neoplasm that arises from the ovary and is characterized by a predominance of clear and hobnail malignant epithelial cells. "We identified a cancer stress response regulator called KEAP1 as a potential target for ARID1A-deficient ovarian clear cell carcinomas." (PMID 39272807, 2024). "In addition, the NRF2 antioxidant pathway is activated in ovarian clear cell carcinomas, possibly due to mutations in the NRF2 negative regulator KEAP1." (PMID 27486766, 2016).
papillary thyroid carcinoma (2 papers, 2019 to 2025). "In papillary thyroid carcinoma (PTC), a handful of KEAP1 alterations have been identified and associated with increased nuclear NRF2 expression, correlating the mutations with NRF2 stabilization." (PMID 41573641, 2025).
periodontal disease (2 papers, 2023 to 2024). "By consulting the relevant literature and performing an integrative bioinformatic analysis, we discovered that miR-141-3p and miR-200a-3p are associated with periodontal disease and regulate NRF2 activity by targeting KEAP1 expression." (PMID 37274022, 2023).
Renal cyst (2 papers, 2014 to 2017). A fluid filled sac in the kidney. "Loss of Fh1 in renal cysts is associated with up-regulation of the Nrf2-mediated antioxidant response pathway because of fumarate-mediated succination of Keap1, which normally promotes Nrf2 degradation." (PMID 28202494, 2017). "Likewise, an accumulation of fumarate modified selected cysteine residues in Keap1 and abrogated the function of Keap1 to promote Nrf2 proteolysis and it led to an increase in the renal cyst formation of fumarate hydratase (FH)-deficient mice." (PMID 25014534, 2014).
skin cancer (2 papers, 2012 to 2020). "In humans, NRF2 activation due to NRF2 or KEAP1 gene mutation plays an important role in the development of skin squamous cell carcinoma, which is the most common type of skin cancer caused by chronic iAs exposure." (PMID 22476201, 2012).
small cell lung carcinoma (2 papers, 2021 to 2022). Small cell lung cancer (SCLC) is a highly aggressive malignant neoplasm, accounting for 10-15% of lung cancer cases, characterized byrapid growth, and early metastasis.
uterine cancer (2 papers, 2014 to 2023). Primary or metastatic malignant neoplasm involving the uterine corpus and/or the cervix. "KEAP1 mutations were predominantly identified in NSCLC cell lines and patients, and have also been detected in several other cancer types, including liver, ovarian, and uterine cancers." (PMID 37633973, 2023).
acne (1 paper, 2024). An inflammatory process of the sebaceous glands which is characterized by comedones, nodules, papules and/or pustules on the skin. "Therefore, agents that interact with KEAP1 protein may liberate and activate the NRF2 pathway, which could further attenuate inflammatory acne." (PMID 38426932, 2024).
acute leukemia (1 paper, 2023). A clonal (malignant) hematopoietic disorder with an acute onset, affecting the bone marrow and the peripheral blood. "We found that the KEAP1 expression was higher in acute leukemias of ambiguous lineage (ALAL) patients compared with normal (p < 0.05)." (PMID 37251921, 2023).
adenovirus infection (1 paper, 2016). "Therefore, Nrf2 overexpression by adenovirus infection may increase the possibility of affecting the physiological role of Nrf2 by infection-induced excessive oxidative stress and Nrf2 overexpression without Keap1 co-transfection." (PMID 27198574, 2016).